FOXP1 (forkhead box P1)
Diseases named in the same sentence as FOXP1 in open-access papers (continued):
Sharing a sentence is not in itself a finding about the gene and the disease.
endometriosis (6 papers, 2021 to 2025). The growth of functional endometrial tissue in anatomic sites outside the uterine body. "A recent study found that FOXP1 expression levels were substantially increased in endometrial mesenchymal cells of patients with endometriosis." (PMID 39629895, 2025). "We performed a series of experiments to confirm the interactions between LINC01116, miR‐9‐5p and FOXP1 in endometriosis." (PMID 33372387, 2021). "Then we considered that LINC01116 promoted the progression of endometriosis via the LINC01116/miR‐9‐5p/FOXP1 axis." (PMID 33372387, 2021). "A previous study has shown that FOXP1 is up‐regulated in endometriosis and promotes cell proliferation, migration and fibrosis via the Wnt/β‐catenin signalling pathway." (PMID 33372387, 2021). "This is the first time that the LINC01116/miR‐9‐5p/Forkhead box protein P1 (FOXP1) axis has been explored in endometriosis." (PMID 33372387, 2021). "Overall, our study illuminates that LINC01116 promotes the progression of endometriosis through the miR‐9‐5p/FOXP1 axis." (PMID 33372387, 2021). "Among them, FOXP1 has been reported to improve cell proliferation and enhance fibrosis in endometriosis, thus FOXP1 was selected as miR‐9‐5p's target gene for further study." (PMID 33372387, 2021). "In addition, FOXP1 promotes endometriosis fibrosis through activation of the wingless related integration site/β‐catenin signaling pathway." (PMID 39629895, 2025). "Moreover, altered FOXP1 expression and Wnt-related β-catenin acetylation were observed in endometriotic stromal cells from endometriosis patients." (PMID 36498516, 2022). "Collectively, these results demonstrate that FOXP1 is a target mRNA of miR‐9‐5p in endometriosis." (PMID 33372387, 2021). "Finally, rescue assays demonstrated that LINC01116 promoted ESCs proliferation and migration by regulating miR‐9‐5p/FOXP1 interaction in endometriosis." (PMID 33372387, 2021). "Suppressing FOXP1 reverted the endometrium cell phenotype, involving decreased collagen gel contraction, cell growth and migratory movement.TCF21 could transactivate SF-1 and Erβ promoters in ESCs, modulating estrogen pathway and fibrosis of endometriosis." (PMID 38844959, 2024). "Similarly, genes shared between endometriosis, uterine fibroids, ovarian cancer, migraine and depression (RHOA, FOXP1, ESR1, WNT4, GREB1, FSHB), and endometriosis, migraine and asthma (IGF1, SMAD3, MFHAS1), were enriched in hormone receptor signalling and inflammation pathways, respectively." (PMID 37159502, 2023).
Huntington disease (6 papers, 2013 to 2023). Huntington disease (HD) is a rare neurodegenerative disorder of the central nervous system characterized by unwanted choreatic movements, behavioral and psychiatric disturbances and dementia. "A similar mechanism is described for Huntington's disease, in which a reduced expression of Foxp1 correlates with the drop of the neuroprotective role in the affected cells." (PMID 37521304, 2023). "Reduced expression of transcription factor FOXP1 and its downstream gene p21Waf1/Cip1 was found to be a contributing factor in Huntington’s disease." (PMID 35741813, 2022). "It was speculated that DRP1 was a marker of cognitive dysfunction and used as a marker in Huntington’s disease, FOXP1 syndrome, and other complicated forms of dementia." (PMID 37563583, 2023).
language disorder (6 papers, 2010 to 2023). A category of disorders characterized by an impairment in the development of an individual's language capabilities, which is in contrast to his/her non-verbal intellect. "In conclusion, we report a previously unknown cause of MR associated with significant speech and language disorder defined by FOXP1 deletions." (PMID 20848658, 2010). "We found that the TBR1 variants abolished interactions with the FOXP1 and FOXP2 transcription factors involved in ID and severe speech/language disorder, respectively." (PMID 30250039, 2018). "FOXP1 is in the same Foxp subfamily as FOXP3; these genes encode for a family of transcription factors recognized for its involvement in autoimmune disease, speech and language disorders, and lung development." (PMID 31324826, 2019). "Here we present the identification of overlapping heterozygous deletions affecting the FOXP1 (MIM# 605515) gene in three unrelated patients with MR and significant speech and language disorder." (PMID 20848658, 2010). "Instead, various screening studies carried out within the last few years have revealed that FOXP1 may be of more global importance in a range of neurodevelopmental disorders, which includes but is not restricted to speech and language disorders." (PMID 22736078, 2012).
neuroblastoma (6 papers, 2014 to 2025). Neuroblastoma (NB) is the most common solid, extracranial childhood tumor. "Array-based CGH analysis of 159 neuroblastomas revealed that heterozygous loss of the FOXP1 locus was a rare event (n = 4), but if present, was associated with low FOXP1 expression." (PMID 25406647, 2014). "Here, we demonstrate that low FOXP1 expression is associated with unfavorable prognostic markers and poor patient outcome in neuroblastoma." (PMID 25406647, 2014). "We also aimed to identify the molecular basis underlying the differential expression of FOXP1 observed in different neuroblastoma subgroups." (PMID 25406647, 2014). "Our results suggest that down-regulation of FOXP1 expression is a common event in high-risk neuroblastoma pathogenesis and may contribute to tumor progression and unfavorable patient outcome." (PMID 25406647, 2014). "We next determined whether FOXP1 expression is associated with neuroblastoma patient event-free survival (EFS) and overall survival (OS)." (PMID 25406647, 2014). "Furthermore, genomic loss at the tumor suppressor locus 3p14.1 including the FOXP1 gene has been described in many cancer types including neuroblastoma and has indicated the presence of a neuroblastoma-associated putative tumor suppressor gene located between 3p14.1 and 3p21.32." (PMID 25406647, 2014). "The prognostic value of FOXP1 expression was substantiated by multivariate Cox regression models based on EFS and OS considering prognostic markers that are currently used for neuroblastoma risk stratification." (PMID 25406647, 2014). "Recombinant FoxP1 protein levels were in the range of physiological levels observed in neuroblastoma patients with high FoxP1 expression." (PMID 25406647, 2014). "The gene forkhead box P1 (FOXP1) maps to chromosome 3p14.1, a tumor suppressor locus deleted in many human cancers including neuroblastoma." (PMID 25406647, 2014). "In summary, our study indicates that aggressive human neuroblastomas show reduced FOXP1 expression, a finding that is compatible with the previously observed loss of FoxP1 in several types of solid tumors." (PMID 25406647, 2014). "To elucidate the role of FoxP1 in neuroblastoma pathogenesis, we examined the expression of FOXP1 in a cohort of 476 primary neuroblastomas using microarrays, and assessed its correlation with prognostic markers and patient outcome." (PMID 25406647, 2014). "Further investigations are required to determine the contribution of these mechanisms to altered FOXP1 expression in neuroblastoma." (PMID 25406647, 2014). "Taken together, these findings indicate that FoxP1 affects growth properties in human neuroblastoma cells by both cell cycle regulation and induction of apoptosis." (PMID 25406647, 2014). "To investigate the mechanisms of FOXP1 downregulation, we determined copy number aberrations of the FOXP1 locus in 159 neuroblastomas by array-CGH as well as DNA methylation patterns of the FOXP1 promoter in 47 tumors using mass spectrometry." (PMID 25406647, 2014). "Together, our observations demonstrate that reconstitution of FOXP1 expression suppresses the malignant phenotype of neuroblastoma cells." (PMID 25406647, 2014). "Indeed re-introduction of FOXP1 into neuroblastoma cells inhibited cell proliferation and colony formation in soft agar, and resulted in cell cycle arrest and apoptosis." (PMID 26367773, 2015). "Although the mechanisms that regulate FOXP1 expression in neuroblastoma remain unclear, low expression of FOXP1 may add predictive value on top of established risk stratification tools in neuroblastoma." (PMID 25406647, 2014). "We therefore speculate that additional molecular mechanisms may mediate FOXP1 gene silencing in neuroblastoma." (PMID 25406647, 2014). "We next examined whether apoptosis may contribute to the inhibition of neuroblastoma cell growth after FOXP1 re-expression." (PMID 25406647, 2014).
neuroblastoma (continued). "Furthermore, we characterized the functional consequences of FOXP1 re-expression on cell proliferation, apoptosis, migration and colony formation in neuroblastoma cell lines." (PMID 25406647, 2014). "In line with this hypothesis, restoration of FOXP1 expression strongly decreased growth rates and tumorigenic characteristics of all three neuroblastoma cell lines analyzed in vitro." (PMID 25406647, 2014). "In four samples, segmental loss of chromosome 3p14.1 comprising the FOXP1 locus was detected, suggesting that deletion of FOXP1 is not a frequent genetic event in neuroblastoma." (PMID 25406647, 2014). "However, deletions of the FOXP1 locus appear to occur rarely in neuroblastoma, suggesting that other factors contribute to differential FOXP1 expression in this malignancy." (PMID 25406647, 2014). "Furthermore, FOXP1 was re-expressed in three neuroblastoma cell lines to study the effect of FOXP1 on growth characteristics of neuroblastoma cells." (PMID 25406647, 2014). "Furthermore, induction of FOXP1 expression led to cell cycle arrest and apoptotic cell death of neuroblastoma cells." (PMID 25406647, 2014). "Analysis of DNA methylation patterns and FOXP1 expression levels did not reveal any correlation, implicating that differential methylation is not a common cause of FOXP1 repression in neuroblastoma." (PMID 25406647, 2014). "Together, these results indicate that FoxP1 may mediate cellular growth restriction in neuroblastoma by cell cycle control, programmed cell death and induction of differentiation." (PMID 25406647, 2014). "The combined effects of intrinsic apoptosis and induction of differentiation have been described to strongly inhibit of proliferation and reduce tumorigenicity of neuroblastoma cells previously, which is well in line with the effects FOXP1 re-expression shown here." (PMID 25406647, 2014). "We noticed that low FOXP1 expression was associated with poor EFS (5-year EFS 0.49 ± 0.03 vs. 0.85 ± 0.02; P < 0.001) and OS (5-year OS 0.60 ± 0.04 vs. 0.93 ± 0.02; P < 0.001), demonstrating that FOXP1 transcript levels discriminate neuroblastoma patients with beneficial and adverse outcome." (PMID 25406647, 2014). "However, loss of FOXP1 was accompanied by low FOXP1 expression levels in all four cases, indicating that low FOXP1 expression may be result from a gene dosage effect in a subset of neuroblastoma." (PMID 25406647, 2014). "Considering that the cell lines used in this study differ in several molecular and biological characteristics like genetic alterations, doubling time, morphology and motility, our results may suggest that diminished FOXP1 expression might act as a growth-promoting factor in neuroblastoma in general." (PMID 25406647, 2014). "In addition, somatic mutations of the coding sequence of FOXP1 have not been identified in recent reports on the mutational spectrum of neuroblastoma using next generation sequencing." (PMID 25406647, 2014). "Together, these findings may suggest a tumor suppressive role of FoxP1 in neuroblastoma." (PMID 25406647, 2014). "Notably, Western blot hybridization analysis revealed that FOXP1 transcript levels correlate well with FoxP1 protein levels, which may indicate that measurement of FOXP1 mRNA is predictive of its functional activity in neuroblastoma." (PMID 25406647, 2014). "The prognostic relevance of low FOXP1 expression was validated by multivariate analysis for OS and EFS, showing that FOXP1 expression predicts neuroblastoma patient outcome independently from well-established prognostic markers." (PMID 25406647, 2014). "First, we examined the methylation status of three DNA regions covering 45 CpG units downstream of the FOXP1 start site in 47 primary neuroblastoma samples and the neuroblastoma cell line IMR-32, which expresses FOXP1 at low levels endogenously." (PMID 25406647, 2014).
neuroblastoma (continued). "Two short hairpin RNA constructs designed against Foxp1, and a scrambled shRNA plasmid as a control that does not target to any mouse gene were tested in mouse neuroblastoma N2a cells and cultured cortical cells." (PMID 26010426, 2015). "By contrast, DNA methylation analysis in 47 neuroblastomas indicated that hypermethylation is not regularly involved in FOXP1 gene silencing." (PMID 25406647, 2014). "While several Fox family members have been shown to play critical roles in neuroblastoma biology, the role of FoxP1 has not yet been investigated in this context." (PMID 25406647, 2014).
breast tumors (5 papers, 2018 to 2024). "To evaluate CD8+ T-cell exhaustion in 4T1 breast tumour-bearing mice, we examined the level of IR mRNAs, including PD-1, TIM-3, BTLA and exhausted T-cell-associated transcriptional factor Foxp1 using reverse transcription quantitative polymerase chain reaction (RT–qPCR)." (PMID 31594465, 2019). "PRMT5 promotes the expansion of stem cells through histone methylation and the expression of forkhead box P1 (FOXP1) and Kruppel-like Factor 4 (KLF4), thereby enabling the development of breast tumors and chemotherapy resistance." (PMID 36230903, 2022). "In addition to known TFs such as GATA3 and FOXP1, we identify HNF1A as a TF specific to luminal A/B breast tumors and LM breast duct cells." (PMID 39478117, 2024).
cardiac hypertrophy (5 papers, 2019 to 2023). "Interestingly, the dysregulation of FOXP1 has been reported to be associated with cardiovascular diseases, including cardiac hypertrophy, coronary heart disease, heart failure and dilated cardiomyopathy." (PMID 37084237, 2023). "FOXP1-knockdown hCMs were larger than control hCMs, a phenotype accompanied by increased expression of cardiac hypertrophy markers NPPA and NPPB." (PMID 37084237, 2023). "In male mice, miR-206 was shown to exacerbate TAC-induced cardiac hypertrophy by targeting tumor suppressor, Forkhead box protein P1 (FoxP1)." (PMID 32252821, 2020). "The downregulation of FOXP1 by miR-206/YAP also leads to the development of cardiac hypertrophy." (PMID 37084237, 2023). "MiR-206 mediates cardiac hypertrophy by inhibiting Forkhead box protein P1 (FoxP1)." (PMID 35269399, 2022). "Mechanistically, miR-206 is positively regulated by Yes-associated protein (YAP), a key molecule of the Hippo pathway, which induces cardiomyocytes apoptosis and hypertrophy, and targets the forkhead box P1 (FoxP1), known to negatively regulate cardiac hypertrophy through inhibition of Nfat3." (PMID 31323768, 2019).
chronic lymphocytic leukemia (5 papers, 2014 to 2025). "Recently, Mraz's group found that the expression of GAB1 and FOXP1 is modulated by miR-150, resulting in proficient B-cell receptor signaling in chronic lymphocytic leukemia, which is consistent with our findings." (PMID 26871477, 2016). "J. Ott and colleagues identified a SE-based CRC in chronic lymphocytic leukemia (CLL) involving PAX5, FOXP1, RARA, ETS1, IRF2, and IRF8, highlighting PAX5's dominant role." (PMID 40083704, 2025). "In addition, our data suggest that non-IG translocations of FOXP1 are implicated in progression of various B-cell neoplasms, including chronic lymphocytic leukemia (CLL)." (PMID 24416450, 2014).
diabetes (5 papers, 2020 to 2025). "Contrary to Meis2, Foxp1, and Cebpb, the expression of Ets1 in endothelial cells gradually declined with the progression of diabetes, with overtly lower levels in clusters 12 and 26 compared with other clusters." (PMID 39475009, 2024). "Of particular alert, several transcription factors were dynamically altered with the progression of diabetes, including Meis homeobox 2 (Meis2), Forkhead box P1 (Foxp1), and CCAAT enhancer binding protein beta (Cebpb)." (PMID 39475009, 2024). "In murine models of diabetes, hepatic FOXP1 expression, a regulator of gluconeogenic gene expression, is downregulated." (PMID 38028628, 2023).
epilepsy (5 papers, 2019 to 2024). A brain disorder characterized by episodes of abnormally increased neuronal discharge resulting in transient episodes of sensory or motor neurological dysfunction, or psychic dysfunction. "Epilepsy and autism spectrum diseases may result from a genetic variation‐related de novo FOXP1 mutation." (PMID 38676299, 2024). "Among almost 100 individuals with FOXP1-related ID syndrome, seven individuals experienced epilepsy, but no subjects have been reported to exhibit movement disorder, suggesting another neurological feature that might occur in this condition." (PMID 37521304, 2023).
gallbladder cancer (5 papers, 2019 to 2023). "For example, FOXP1 drives the occurrence of malignant behaviour by dominating the expression level of PKLR in gallbladder cancer." (PMID 36160018, 2022). "In gallbladder cancer, our previous study showed that circular RNA FOXP1 promotes tumor progression and Warburg effect in gallbladder cancer by regulating PKLR expression." (PMID 34489401, 2021).
osteoporosis (5 papers, 2020 to 2024). A condition of reduced bone mass, with decreased cortical thickness and a decrease in the number and size of the trabeculae of cancellous bone (but normal chemical composition), resulting in increased fracture incidence. "Studies have shown that ASCs can promote the density and formation of bone tissues for osteoporosis by upregulating Forkhead Box P1 (FOXP1) expression levels." (PMID 39601916, 2024).
speech delay (5 papers, 2015 to 2023). "FOXP1 is associated with ASD, speech delay, and intellectual disability." (PMID 33795679, 2021).
acute myeloid leukemia (4 papers, 2014 to 2025). Acute myeloid leukemia (AML) is a group of neoplasms arising from precursor cells committed to the myeloid cell-line differentiation. "FOXP1 deletions have been described in acute myeloid leukemia and myelodysplastic syndrome, but the evidence for their clinical relevance is currently not strong." (PMID 38605095, 2024). "FOXP1 was also found activated in other patients with myelodysplasia and acute myeloid leukemia, showing that it is an important, recurrent event." (PMID 24893616, 2014). "Finally, our results may suggest a possible broader role of FOXP1 in the pathogenesis and progression of myelodysplasia and acute myeloid leukemia." (PMID 24893616, 2014).
Autoimmunity (4 papers, 2022 to 2025). The occurrence of an immune reaction against the organism's own cells or tissues. "Upregulation of FOXP1 in the present study supports T cells in the distal intestine being mainly inducible Treg that are critically important in maintaining tolerance and preventing autoimmunity." (PMID 39015564, 2024). "The combined loss of FOXP1 and FOXP4 in committed Treg cells results in increased cellularity of activated T cells, inflammatory cytokine secretion, GC B cell responses, and pathogenic antibody production resulting in systemic inflammation, autoimmunity, lymphoproliferation, and decreased lifespan." (PMID 40794436, 2025). "Our findings show that mice with combined, but not individual, deficiency in FOXP1 and FOXP4 exhibit lymphoproliferation, inflammation, autoimmunity, and early lethality." (PMID 40794436, 2025).